S100A10 (S100 calcium binding protein A10)
Diseases named in the same sentence as S100A10 in open-access papers (continued):
Sharing a sentence is not in itself a finding about the gene and the disease.
lung carcinoma (8 papers, 2016 to 2024). "Recent research indicates that S100A10 serves as a novel predictive factor for clinical diagnosis, prognosis, and immunotherapy response in lung cancer patients." (PMID 39117605, 2024). "The displacement of S100A10 from annexin A2 attenuates plasminogen activation, impairing colony formation and growth of A549 lung cancer cells." (PMID 30572596, 2018). "The overexpression of S100A10 is related to the poor prognosis of lung cancer." (PMID 35437508, 2022). "Additionally, S100A10 also regulated the metastasis of lung cancer cells by the interaction with DLC1." (PMID 34178044, 2021). "In this study, we reviewed S100A10 modulates tumor progression through macrophage activities and Ras signaling pathway, including the promoting role in the initiation and development of acute promyelocytic leukemia and lung cancer." (PMID 31949486, 2020). "Additionally, experimental studies have shown that S100A10, a recently identified binding partner of DLC1, regulates invasion of human lung cancer cells." (PMID 31739800, 2019). "The displacement of S100A10 from annexin A2 by DLC1, a Rho GTPase-activating protein (RhoGAP) that functions as a tumor suppressor, results in the attenuation of plasminogen activation and impaired invasion of A549 lung cancer cells." (PMID 30572596, 2018).
melanoma (8 papers, 2019 to 2025). A malignant, usually aggressive tumor composed of atypical, neoplastic melanocytes. "The expression of one of the S100 proteins, S100A10 (hypothesized to be associated with cell proliferation), was downregulated in three melanoma cell lines (G-361, A375 and MeWo) compared to normal melanocytes (HEMn cell line)." (PMID 35807436, 2022). "In melanoma S100A10 binds the CCR10 cytosolic tail, linking it to annexin A2 and regulating CCR10 surface expression; S100A10 knockdown increases CCR10 levels and disrupts annexin A2 association, underscoring its role in CCR10 localization and stability." (PMID 41050670, 2025). "Of the three melanoma cell lines, MeWo showed higher S100A10 expression." (PMID 35807436, 2022). "Interestingly, when compared to normal skin samples, they found that S100A10 expression was high in primary melanoma and low in metastatic melanoma." (PMID 34944416, 2021). "In transdifferentiated A375 cells the melanoma markers MKI67, MITF, S100A4, S100A10, MMP2 and MMP9 were significantly downregulated." (PMID 40715046, 2025). "S100A10 and GNG12 proteins are known to play roles in melanoma malignancy and the expression levels of these two proteins were higher in WM989 melanoma cells from both BCP and SCP datasets." (PMID 38621647, 2024). "To address the biological significance of K47 succinylation in vivo, we performed mouse melanoma lung metastasis experiments using stable B16F10 cell lines overexpressing WT, K47R or K47E mutant S100A10." (PMID 30394687, 2019). "Indeed, in the context of melanoma xenograft tumors, we showed that overexpression of RAGE resulted in the upregulation of S100A2, S100A4, S100A6, and S100A10, both at the transcript and protein levels." (PMID 37627239, 2023). "Unlike S100A10 expression in other types of cancer, lower expression levels may be a biomarker for malignant melanoma." (PMID 34944416, 2021).
fibrosarcoma (7 papers, 2007 to 2024). A malignant mesenchymal fibroblastic neoplasm affecting the soft tissue and bone. "Our initial studies, which were the first to examine cancer cell growth and invasion with the S100A10-knockout mouse, revealed that the growth of murine Lewis lung carcinomas or T241 fibrosarcomas was dramatically reduced in the S100A10-deficient mice compared with wild-type mice." (PMID 34944416, 2021). "The growth of Lewis Lung carcinoma (LLC) and T241 fibrosarcomas is greatly reduced in S100A10 knockout mice compared with wild-type mice." (PMID 30572596, 2018). "S100A10 mediates macrophage migration to tumor sites and increases fibrosarcoma invasion." (PMID 34148033, 2021). "These and our subsequent studies with A549, PANC-1, Lewis lung carcinoma, T241 fibrosarcoma, NB4, thioglycollate-elicited macrophages, and TIME cells have demonstrated that S100A10 accounts for 50–90% of cellular plasmin generation." (PMID 34944416, 2021). "S100A10 plays an important role in this process, as overexpression of S100A10 in HT1080 fibrosarcoma was shown to increase the lung metastatic burden in mice by 16-fold while the loss of S100A10 reduced the metastatic burden by 3-fold." (PMID 30572596, 2018). "For example, mice deficient in the plasminogen receptor S100A10 did not support tumor growth of subcutaneously injected LLC and fibrosarcomas." (PMID 37971174, 2024).
leukemia (7 papers, 2018 to 2024). A malignant (clonal) hematologic disorder, involving hematopoietic stem cells and characterized by the presence of primitive or atypical myeloid or lymphoid cells in the bone marrow and the blood. "In PML-RARα-associated APML expression of the ANXA2/S100A10 complex causes hyperfibrinolysis due to the accumulation of plasmin on the surface of leukemia cells." (PMID 39567540, 2024). "S100A10 antibody plays an important role in reducing homing of leukemia cells to the bone marrow in vivo." (PMID 33324631, 2020). "High expression of S100A10 is essential for ANXA2 phosphorylation mediated by Src kinase in leukemia." (PMID 33324631, 2020). "High S100A10 expression has a link to poor outcomes and chemoresistance in several types of cancer, including leukemia." (PMID 33134167, 2020). "S100A10 antibodies are effective in reducing leukemia cell invasion in vitro and homing of leukemia cells to the bone marrow in vivo." (PMID 30572596, 2018). "S100A10 together with annexin A2 has been shown to regulate the adhesion of leukemia cells and prostate cancer cells to osteoblasts." (PMID 30572596, 2018). "Treatment with small molecules that inhibit the S100A10–annexin A2 interaction, antibodies against annexin A2 and S100A10, or the knockdown of S100A10 could all increase the sensitivity of NTPL-20 leukemia cells to the chemotherapy drug vincristine." (PMID 30572596, 2018). "By performing network analysis based on physical interactions and co-expression, we demonstrated that the upregulated genes LGALS1, S100A10, EMP3, and S100A4 in the residual leukemia-like cells were involved in a functional module with LGALS1 as a hub gene." (PMID 36543880, 2023). "The role of S100A10 in cancer was first identified in acute promyelocytic leukemia (APL), a subtype characterized by the expression of a fusion protein formed by the fusion of retinoic acid receptor alpha with promyelocytic leukemia (PML-RARα) genes." (PMID 30572596, 2018).
pancreatic ductal adenocarcinoma (7 papers, 2016 to 2023). An infiltrating adenocarcinoma that arises from the epithelial cells of the pancreas. "Overexpression of S100A10 is associated with a poor prognosis of pancreatic ductal adenocarcinoma." (PMID 34804125, 2021). "In Badea’s datasets, higher expressed S100A10/A11 were found in pancreatic ductal adenocarcinoma ((fold change = 3.1 and 4.43)." (PMID 34804125, 2021). "S100A10 is also being considered as a biomarker in pancreatic ductal adenocarcinoma." (PMID 37627239, 2023). "We have also addressed whether S100A10 plays a role in in vivo pancreatic ductal adenocarcinoma (PDAC)." (PMID 34944416, 2021). "The expression of S100A10 was low in pancreatic nonductal stroma and normal tissue and unchanged even if the normal ducts or nonductal stroma were adjacent to pancreatic intraepithelial neoplasia (PanIN) or pancreatic ductal adenocarcinoma (PDAC)." (PMID 34944416, 2021).
prostate carcinoma (7 papers, 2011 to 2024). A carcinoma that arises from epithelial cells of the prostate gland. "In our study, for the first time, we have identified increased expression of SCARB1 and MAPK3K1 and decreased expression of S100A10 in PCAFs compared to PNAFs even if the role of these genes in prostate cancer progression and androgen resistance is well known." (PMID 35740605, 2022). "S100A11 and S100A10 are calcium binding proteins and their increased expression are often observed in colorectal and prostate cancer, including non-small cell lung cancer." (PMID 21909426, 2011). "However, there are also some researchers who hold the opposite view that S100A10 and Annexin A2 are positively correlated with the malignancy of prostate cancer." (PMID 31949486, 2020). "Furthermore, a recent mass spectrometric comparison of epithelial-like and mesenchymal-like ARCaP prostate cancer cells revealed that S100A10 was one of 76 proteins that were significantly increased in the mesenchymal-like cells." (PMID 30237490, 2018). "However, reduced S100A10 expression has also been reported in prostate cancer and thyroid carcinoma." (PMID 30572596, 2018). "We found that SCARB1 expression positively correlated with prostate cancer, nodal metastasis status, and Gleason score while MAPK3K1 and S100A10 levels inversely correlated." (PMID 35740605, 2022). "Additionally, while CDC20, COL1A2 and S100A10 possess recognized pro-oncogenic activities, the precise roles of B4GALNT4 and NUAK1 in prostate cancer warrant elucidation." (PMID 39391236, 2024). "Interestingly, bioinformatic analysis based on the TGCA dataset showed that SCARB1 expression was significantly increased in prostate cancer samples compared to normal tissues while MAPK3K1 and S100A10 expression was significantly reduced." (PMID 35740605, 2022). "Generally, there is not a specific conclusion that how S100A10 influences prostate cancer." (PMID 31949486, 2020).
glioma (6 papers, 2014 to 2025). A benign or malignant brain and spinal cord tumor that arises from glial cells (astrocytes, oligodendrocytes, ependymal cells). "This study aimed to reveal the underlying mechanism by which S100A10 in regulates the proliferation, migration, and invasion of glioma." (PMID 37476183, 2023). "miRDB and double luciferase assay were used to predict and identify potential S100A10 mRNA-complementary miRNAs, and the roles of miR-21-5p in glioma cell were examined by targeted knockdown or overexpression miR-21-5p in glioma cell lines." (PMID 37476183, 2023). "The functional roles of S100A10 in glioma were assessed by cell counting kit-8 (CCK-8) cell proliferation assay, wound healing assay, transwell assay, and flow cytometry." (PMID 37476183, 2023). "We found that S100A10 was overexpressed in glioma tissues and predicted a worse prognosis." (PMID 37476183, 2023). "This study showed S100A10 was a new prognostic predictor among glioma patients and provided new insights into the pathogenesis of gliomas, suggesting that miR-21-5p /S100A10 axis may serve as a valuable therapeutic target for glioma." (PMID 37476183, 2023). "S100A10 knockdown significantly inhibited glioma cell proliferation, invasion, and migration." (PMID 37476183, 2023). "Furthermore, we demonstrated that miR-21-5p inhibits glioma proliferation, migration, and invasion by targeting S100A10." (PMID 37476183, 2023). "In addition to P-gp, mitochondria, and CD31, we explored the spatial and amount distribution of the S100A10 as a specific biomarker of glioma cells." (PMID 36553127, 2022). "Specifically, S100A8 and S100A9 were expressed in myeloid cells, S100A10 and S100A11 in various cell types, especially in glioma tumor cells, and S100A13 and S100A16 in vascular cells." (PMID 39744679, 2025). "In our data, S100A10 and S100A11 had the strongest correlation with the immune cell infiltration in glioma." (PMID 34148033, 2021). "S100A10 expression levels in glioma tumor tissues and adjacent nontumor tissues were compared by immunohistochemistry (IHC)." (PMID 37476183, 2023). "A member of this family, S100A10, is a specific biomarker of differentiated non-stem glioma cells mediating cell–cell contact among glioma cells and ECs." (PMID 36553127, 2022).
ischemia (6 papers, 2020 to 2025). A hypoperfusion of the BLOOD through an organ or tissue caused by a PATHOLOGIC CONSTRICTION or obstruction of its BLOOD VESSELS, or an absence of BLOOD CIRCULATION. "Our data, however, would suggest that BCAS 14d and 28d mouse brains showed evidence of an anti-inflammatory or neuroprotective state as shown by a significant increase in the expression of S100A10, IL-10, Nrf2, and TRPA1, all of which have been linked to ischemia-induced neuroprotection." (PMID 40895091, 2024). "In the current study, we found that the expression of S100A10 in astrocyte decreased at day 2 post-ischemia, but then increased by 4–14-day post-ischemia, peaking at day 7, and declining at day 14, and this is almost identical to the dynamic changes of KLF4 in astrocytes following ischemic stroke." (PMID 36823628, 2023). "To explore whether microglia regulate astrocytes after ischemia, we examined the temporal profiles of microglial activation and reactive astrocytes, particularly in C3d and S100A10 expression, from the acute to chronic stages of stroke in rats subjected to MCAO." (PMID 37676390, 2024). "However, KLF4 was always co-stained well with S100A10 in the penumbra at days 2, 4 and 7 post-ischemia, especially at day 7, KLF4 co-localized with S100A10 extensively." (PMID 36823628, 2023).
liver cancer (6 papers, 2020 to 2025). An epithelial or non-epithelial malignant neoplasm that arises from the liver. "This research offers valuable insights into the molecular mechanisms underlying LIHC and suggests S100A10 as a promising target for enhancing treatment outcomes in liver cancer patients." (PMID 39840058, 2024). "However, these two closely associated proteins present opposite contributions to hepatic cancer, S100A10 being protective and S100A11 deleterious." (PMID 40841353, 2025). "In concert with S100A11, ANXA2 is described as a driver of liver cancer and S100A10 controls the activity of ANXA2." (PMID 40841353, 2025). "From this perspective, we decided to over-express S100A10 to mitigate liver cancer incidence/growth." (PMID 40841353, 2025). "Overall, our study highlighted for the first time an hepatoprotective contribution of S100A10 on liver cancer." (PMID 40841353, 2025). "Future studies should aim to expand the sample size to better analyze the function of S100A10 in liver cancer and its relationship with stem cells." (PMID 39840058, 2024). "The results of this study highlight S100A10 as an essential predictor for liver cancer diagnosis and treatment response, particularly regarding immunotherapy." (PMID 39840058, 2024). "Our findings indicated that S100A10 possesses a notable predictive value for liver cancer diagnosis (AUC=0.686)." (PMID 39840058, 2024). "We also analyzed the expression levels of S100A10 in liver cancer samples, revealing that its expression was significantly higher in liver cancer compared to normal liver tissue." (PMID 39840058, 2024). "Members of the S100 calcium binding protein family, namely, S100A7, S100A8, S100A9, and S100A10, exert a momentous function in tumor growth and metastasis, such as breast and liver cancer." (PMID 36421685, 2022). "Furthermore, the KM curve analysis demonstrated that patients with elevated S100A10 expression have a poorer prognosis, and S100A10 expression can also serve as a predictor for the 1-year, 2-year, and 3-year prognosis of liver cancer patients." (PMID 39840058, 2024). "In addition, our study was conducted through the analysis of multiple data sets, confirming the expression of the stem cell-related gene S100A10 in liver cancer, albeit based on a limited number of experiments." (PMID 39840058, 2024). "In addition, we investigated the interaction of S100A10 with therapeutic agents for LIHC, and the findings demonstrated that S100A10 has a substantial binding affinity to these drugs, underscoring its potential as a therapeutic target for liver cancer." (PMID 39840058, 2024). "Additionally, we assessed the predictive value of S100A10 for diagnosing liver cancer using the ROC curve." (PMID 39840058, 2024). "Here, we investigated the impact of hepatocyte downregulation of two closely-related members of the S100 family, S100A10 and S100A11, in complementary mouse models of MASLD and liver cancer." (PMID 40841353, 2025). "Since etiology of liver cancer is multifactorial and multigenic, we next investigated the respective roles of S100A10 and S100A11 in an additional mouse model with or without the contribution of MASLD." (PMID 40841353, 2025). "IN HPA database, immunohistochemistry showed that the expressions of APEX1, ME1, S100A10 and ACACA in liver cancer tissues were significantly higher than those in paired normal liver tissues, while ADH1C, and CYP2C9 were expressed at low levels in tumor tissues compared with adjacent normal tissues." (PMID 36456877, 2022). "As no rodent model faithfully recapitulate the whole complexity of human MASLD and HCC, we investigated the roles of S100A10 and S100A11 using complementary mouse models of MASLD, MASLD-driven HCC, or liver cancer without metabolic disorders." (PMID 40841353, 2025).
Stroke (6 papers, 2020 to 2025). Sudden impairment of blood flow to a part of the brain due to occlusion or rupture of an artery to the brain. "This has major implications in terms of a physiological role for S100A10 in mitigating the deleterious effects of stroke and as a potential therapeutic agent for augmenting tPA-dependent thrombolytic therapy." (PMID 37892132, 2023). "This study showcased the importance of S100A10 in the endothelial cell fibrinolytic surveillance system in vivo and has broad-reaching implications for stroke, cardiovascular diseases, and cancer progression." (PMID 37892132, 2023). "In contrast, stroke-induced genes (Clcf1, Tgm1, S100a10) showed a transient increase at 3 days that was reduced by 7 days." (PMID 35350551, 2022).
acute promyelocytic leukemia (5 papers, 2016 to 2023). An aggressive form of acute myeloid leukemia (AML), characterized by arrest of leukocyte differentiation at the promyelocyte stage, due to a specific chromosomal translocation t(15;17) in myeloid cells. "In acute promyelocytic leukemia (APL), we have shown that cell surface S100A10 expression in APL cells is responsible for the increased fibrinolytic events associated with APL patients." (PMID 37892132, 2023). "The first link between plasminogen receptors and oncogenic transformation of cells was the report that S100A10 was upregulated by the oncogene responsible for acute promyelocytic leukemia (APL), PML-RARα." (PMID 27351226, 2016). "S100A10 is also responsible for the hyperfibrinolytic syndrome exhibited by patients with acute promyelocytic leukemia (APL)." (PMID 27351226, 2016).
bladder cancer (5 papers, 2020 to 2023). "Another lncRNA, KCNMB2-AS1, functions by regulating S100A10 in bladder cancer through direct sponging of miR-374a-3p, which negatively regulates the expression of S100A10." (PMID 37892132, 2023). "In conclusion, Lnc KCNMB2-AS1 serves as a ceRNA of miR-374a-3p in upregulating the expression of S100A10, thus promoting bladder cancer progression." (PMID 34367236, 2021). "In conclusion, our results demonstrated that lncRNA KCNMB2-AS1 can promote the progression of bladder cancer through regulation of miR-374a-3p/S100A10." (PMID 34367236, 2021).